KDM6A (lysine demethylase 6A)
Diseases named in the same sentence as KDM6A in open-access papers (continued):
Sharing a sentence is not in itself a finding about the gene and the disease.
autoimmune disease (12 papers, 2020 to 2024). A disorder resulting from loss of function or tissue destruction of an organ or multiple organs, arising from humoral or cellular immune responses of the individual to their own tissue constituents. "KDM6A/B inhibition also comprises a potent anti-inflammatory approach in inflammatory and autoimmune disorders associated with inappropriately exuberant inflammatory and autoimmune responses, restoring immunological homeostasis to inflamed tissues." (PMID 35915507, 2022). "Given the key function of KDM6A in regulating CD4+ T cells, concluded that KDM6A likely regulates multiple immune response genes in autoimmune disease susceptibility." (PMID 34051747, 2021). "The same overexpression of KDM6A appears to be involved with sex differences in autoimmune disease susceptibility, contributing to a higher incidence of multiple sclerosis in females." (PMID 34646300, 2021). "The X-linked gene Kdm6a, which escapes X inactivation, may be of interest, given its link to sex-biased risk for autoimmune diseases and Alzheimer’s disease." (PMID 38750146, 2024). "Interestingly, higher expression of Kdm6a in females has also been linked to neuroinflammation in mice, which might help shed light on women’s increased susceptibility to autoimmune diseases of the central nervous system such as multiple sclerosis." (PMID 36293143, 2022). "KDM6A is a histone demethylase on the X chromosome, and ablation of KDM6A has been found to repress neuropathology in autoimmune disease via inactivating the neuroinflammation signaling pathways." (PMID 34122720, 2021). "Elevated KDM6A expression in female CD4 + T cells also contributes to the mitigation of experimental autoimmune encephalomyelitis (EAE), influencing sex-based susceptibility to autoimmune diseases such as MS." (PMID 39731171, 2024). "The authors postulated that sexually dimorphic expression of KDM6A in immune cells could provide insights into why more women than men generally develop autoimmune diseases." (PMID 33183347, 2020). "Another gene implicated in immune responses against viral infections and in autoimmune diseases is KDM6A, coding an epigenetic regulator (lysine-specific demethylase 6A)." (PMID 34200989, 2021). "KDM6A has been reported to have roles in the function of Treg cells and CD4 T cells in autoimmune disease and maintenance of Th17 (T-helper cell 17) CD4 T cell responses." (PMID 32731355, 2020). "Interestingly, KDM6A is an X-linked gene that escapes X-chromosome inactivation in females, and KDM6A deletion in CD4+ T-helper cells resulted in autoimmunity amelioration in the context of multiple sclerosis, which is also a female-biased autoimmune disease." (PMID 38067106, 2023). "Moreover, in female ankylosing spondylitis patients, inflammatory KDM6A expression in Th17 cells correlates with increased transcriptional ratios of immune-regulatory KDM5C, suggesting potential targets for T cell-driven therapies in autoimmune diseases." (PMID 39731171, 2024).
colorectal cancer (12 papers, 2021 to 2025). A primary or metastatic malignant neoplasm that affects the colon or rectum. "In this study, we utilized a conditional knockout mouse model of KDM6A to investigate its function in colorectal cancer, and explored the underlying mechanisms." (PMID 38840262, 2024). "It has been reported that colorectal cancer (CRC) with lymph node metastasis has a higher frequency of KDM6A mutations." (PMID 38840262, 2024). "In summary, this study demonstrated that KDM6A promotes the progression of colorectal cancer by upregulating LDHA and glycolysis." (PMID 38840262, 2024). "Previous studies have suggested that inhibiting the demethylase activity of KDM6A can suppress cancer stem cells and inhibit the progression of colorectal cancer." (PMID 38840262, 2024). "It seems that the functions of KDM6A in colorectal cancer have been controversial, and further investigation is urgently needed to clarify its role in colorectal cancer." (PMID 38840262, 2024). "During cell culture, we observed that the culture medium of cells with knocked down KDM6A expression turned yellow, indicating increased acid production in colorectal cancer cells after KDM6A knockdown." (PMID 38840262, 2024). "Then, we knocked down KDM6A expression in colorectal cancer cell lines and used CCK8 assay, soft agar colony formation assay, and EdU assay to detect the effects of KDM6A knockdown on the growth and proliferation of colorectal cancer cells." (PMID 38840262, 2024). "Overexpression of KDM6A reduced lactate levels in colorectal cancer cells, while knockdown of KDM6A increased lactate levels." (PMID 38840262, 2024). "The results showed that knocking down KDM6A expression promoted the growth of colorectal cells in liquid culture medium and enhanced the colony formation ability of colorectal cancer cells on soft agar." (PMID 38840262, 2024). "In order to study the function of KDM6A in the development of colorectal cancer, we used AOM/DSS treatment to induce colorectal cancer." (PMID 38840262, 2024). "One of the interesting findings of this study is the illustration of the roles of KDM6A in the progression of colorectal cancer." (PMID 38840262, 2024). "In addition, studies have shown that inhibiting the demethylase activity of KDM6A can eliminate colorectal cancer tumor-initiating cells and suppress tumor development." (PMID 38840262, 2024). "Therefore, this study elucidates the mechanism by which KDM6A regulates glycolysis, and suggests LDHA as a therapeutic target for colorectal cancer carrying KDM6A mutations." (PMID 38840262, 2024). "On the other hand, knocking down KDM6A expression promoted the growth of colorectal cancer cells." (PMID 38840262, 2024). "Although mutations and inactivation of KDM6A have been reported in colorectal cancer, there is currently no report on the role of KDM6A in maintaining intestinal epithelial homeostasis and its function in colorectal progression." (PMID 38840262, 2024). "However, some reports claim that higher expression of KDM6A predicts the advanced colorectal cancer." (PMID 38840262, 2024). "It was found that the protein levels of KDM6A was downregulated in colorectal cancer cell lines." (PMID 38840262, 2024). "Furthermore, the function of KDM6A in colorectal cancer also depends on the expression of LDHA." (PMID 38840262, 2024). "KDM6A (lysine demethylase 6A) has been reported to undergo inactivating mutations in colorectal cancer, but its function in the progression of colorectal cancer has not been evaluated using animal models of colorectal cancer." (PMID 38840262, 2024). "In this study, we used KDM6A conditional knockout mouse model and found that KDM6A deletion resulted in elongation of villi and crypts in the small intestine, and accelerated the development of AOM/DSS-induced colorectal cancer." (PMID 38840262, 2024).
colorectal cancer (continued). "Consistent with this, in our molecular mechanism study, we found that KDM6A regulates LDHA expression by interacting with HIF-1alpha, promoting glycolysis, and subsequently promoting colorectal cancer progression." (PMID 38840262, 2024). "Next, we examined the protein levels of KDM6A in normal epithelial cells (NCM460) and colorectal cancer cell lines." (PMID 38840262, 2024). "Inactivation of KDM6A leads to changes in H3K27 methylation, increasing the stemness of colorectal cancer stem cells and promoting chemoresistance." (PMID 38840262, 2024). "Immunoblotting analysis of clinical colorectal cancer samples revealed that KDM6A expression was markedly reduced in CAFs compared to non-activated fibroblasts (NAFs) from the adjacent non-cancerous tissue." (PMID 40659611, 2025). "In this study, we found that knocking out KDM6A expression in mouse intestinal epithelium increased the length of villus and crypt, promoting the development of AOM (azoxymethane)/DSS (dextran sulfate sodium salt)-induced colorectal cancer." (PMID 38840262, 2024). "Mechanistically, PCGF1 promotes the expression of the colorectal cancer stemness markers CD133, CD44 and ALDH1A1 by maintaining histone H3K4me3 and removing histone H3K27me3 marks by increasing the expression of the H3K4me3 methyltransferase KMT2A and the H3K27me3 demethylase KDM6A." (PMID 34148069, 2021). "Therefore, it is possible that the inhibitory effect of KDM6A on colorectal cancer development may not rely on its demethylase activity." (PMID 38840262, 2024).
glioblastoma (11 papers, 2020 to 2026). The most malignant astrocytic tumor (WHO grade IV). "In male glioblastoma patients, lower KDM6A expression compared to females is linked to higher levels of immune suppression and T-cell exhaustion, resulting in a less effective immunotherapy response." (PMID 40303343, 2025). "KDM6A has also been identified as a critical target for immunotherapy in glioblastoma." (PMID 40303343, 2025). "In the specific case of glioblastomas, these authors found proof of biallelic expression in females of KDM6A (encodes the lysine-specific demethylase 6A), KDM5C (encodes the lysine demethylase 5C), DDX3X (encodes a DEAD-box helicase 3 X-linked), and ATRX (encodes the ATRX chromatin remodeler)." (PMID 33752729, 2021). "In male glioblastoma (GBM) patients, KDM6A-induced T cell exhaustion correlates with GBM progression and response to immune therapies." (PMID 39731171, 2024). "The transition to the persistent state of glioblastoma stem cell (GSC) is dependent on the upregulation and widespread redistribution of histone demethylases KDM6A/B." (PMID 33752729, 2021). "Similarly, a study investigating sex disparities in glioblastoma (GBM) reveals higher incidence and mortality rates in male dependent on KDM6A expression in CD8+ T cells." (PMID 41019050, 2025). "Intriguingly, we also noticed that the expression of KDM6A remained unchanged in esophageal squamous cell carcinoma (ESCC) and glioblastoma (GBM) in comparison with para-cancerous tissues." (PMID 38850159, 2024). "Interestingly, upregulation of KDM6A and KDM6B is also observed in DTCs from glioblastoma." (PMID 37638338, 2023).
Intellectual disability (11 papers, 2013 to 2025). "Copy number gains of the X-linked gene KDM6A, which has a surviving human Y homolog, are found in patients with developmental abnormalities and intellectual disability." (PMID 29449410, 2018). "Patients with protein-truncating mutations in KDM6A versus protein-altering variants may also display more severe intellectual disability." (PMID 36292647, 2022). "As HI can be the presenting feature of KS and intellectual disability and facial dysmorphism are often not prominent until later in childhood, the absence of a clinical diagnosis of KS could not preclude the KDM6A variants being disease-causing." (PMID 39078990, 2025). "Other members of the KDM family were also been identified as the disease genes for syndromic mental retardation, including KDM5C (MIM:314690) and KDM6A (MIM: 300128)." (PMID 27257017, 2016). "Of the genetic defects found outside the MD gene panel, seven genetic defects were found in genes present in the intellectual disability gene panel (ARID1B, SCN1A, ASPM, CTNNB, KDM6A, SMARCA4 and SETBP1)." (PMID 25735936, 2015).
Obesity (10 papers, 2016 to 2025). Accumulation of substantial excess body fat. "Given that ER stress has been linked to obesity in vivo, to further examine the potential physiological effect of Kdm6a in vivo, we established inducible knockout mice and selected a high‐fat diet‐induced obesity model." (PMID 34306972, 2021). "Metformin, a more commonly used drug for T2DM, directly targets the H3K27me3 demethylase KDM6A and can reverse the H3K36me mark in prediabetic and diet-induced obesity mouse models." (PMID 39062577, 2024). "Inhibition of KDM6A reduces Cry1 expression and sensitizes leptin signaling to combat obesity‐related diseases." (PMID 35087408, 2021). "The results show that inhibition of Kdm6a reduces the Cry1 expression and sensitizes leptin signaling to combat obesity‐related disease." (PMID 34306972, 2021). "This study provides a new target for antiobesity strategies, expands the potential applications of Kdm6a inhibitors to combat obesity." (PMID 34306972, 2021). "Although Kdm6a is a target of the well-known antidiabetic drug metformin, the physiological role of Kdm6a in metabolic diseases, such as obesity and diabetes, is not fully understood." (PMID 33303977, 2021). "With the ChIP‐Seq and mRNA microarray assays, a critical role is identified for Kdm6a in the regulation of H3k27me3 to impact the expression of Crytochrome 1 (Cry1) in the hypothalamus of diet induced obesity mice." (PMID 34306972, 2021). "Inhibition of Kdm6a restores the H3k27me3 modification, reduces the Cry1 expression in the hypothalamus, and sensitizes leptin signaling to combat obesity‐related disease." (PMID 34306972, 2021). "Together with our mouse data, these results suggest that Kdm6a inhibition sensitizes leptin signaling to reduce obesity‐related properties." (PMID 34306972, 2021). "In conclusion, Kdm6a in macrophages drives obesity and metabolic syndrome by impairing BAT activity and WAT differentiation." (PMID 33303977, 2021). "Coordination between the inhibition of HDAC1 and the activation of the histone demethylase Lysine-specific demethylases 6 (KDM6B/JMJD3A) and KDM6A/UTX activates brown adipocyte genes and prevents the appearance of obesity." (PMID 31614705, 2019). "Coordination between the inhibition of HDAC1 and the activation of the histone demethylase lysine-specific demethylases (KDM6b/JMJD3a) and KDM6a/UTX activates brown adipocyte genes and prevents the appearance of obesity." (PMID 27528872, 2016). "Moreover, C‐C motif chemokine 2 (CCL2) and KDM6A expression was higher in the group with obesity, as were CREBBP and EP300." (PMID 40518865, 2025). "Consequently, GSK-J4, a KDM6A inhibitor, serves as an attractive drug for obesity and metabolic disorders." (PMID 39062577, 2024). "We first examined whether Kdm6a is involved in HFD-induced obesity (DIO) and metabolic inflammation in obese mice." (PMID 33303977, 2021). "Therefore, GSK-J4, a KDM6A inhibitor, could serve as an attractive drug for obesity and metabolic disorders." (PMID 35087408, 2021). "Therefore, it implicates Kdm6a as an attractive drug target for obesity and metabolic disorders." (PMID 34306972, 2021). "Specifically, we observed elevated levels of KDM6A, CREBBP, and EP300 histone modifiers in ASCs from patients with obesity class II‐III." (PMID 40518865, 2025). "In the vWAT progenitor cells (ASCs), there was a substantial increase in CCL2 and an increase in the expression of KDM6A, as well as the acetylases CREBBP and EP300 in the patients with obesity." (PMID 40518865, 2025). "We hypothesize that obesity modulates histone H3K27 marks, modified by demethylases (lysine‐specific demethylase 6A and 6B [KDM6A/KDM6B]) and acetylases (CREB–binding protein [CREBBP]/histone acetyltransferase EP300), affecting ASC function." (PMID 40518865, 2025). "Myeloid-specific Kdm6a knockout in Kdm6aF/Y;Lyz2-Cre mice significantly reversed the high-fat diet (HFD)-induced M1–M2 imbalance in white adipose tissue (WAT) and blocked HFD-induced obesity." (PMID 33303977, 2021).
urothelial bladder carcinoma (10 papers, 2018 to 2025). "Transcriptome analysis found several disrupted pathways, particularly the PRC2/EZH2 pathway, in KDM6A-mutated urothelial bladder carcinoma." (PMID 40308577, 2025). "There was one instance (i.e., a combination of gene and cancer type) where RNA VAF repeatedly identified (Fisher’s exact test, p < 0.1) putative driver mutations among BoostDM passengers: KDM6A in urothelial carcinoma of the bladder." (PMID 40514689, 2025). "In UTX/KDM6A-mutated urothelial bladder carcinoma, PRC2/EZH2 target genes, such as IGFBP3, are deregulated due to H3K27me3 enrichment." (PMID 31221981, 2019). "Furthermore, extensive mutations in KDM6A were identified in urothelial bladder carcinoma, with about 70% resulting in loss of gene expression and demethylase activity." (PMID 40308577, 2025). "Additionally, by searching and integrating other published data, they found that KDM6A mutations appeared in 29% of the urothelial bladder carcinoma samples." (PMID 36052737, 2022). "Scholars have reported that EZH2 can repress multiple downstream targets (e.g., KDM6A, GIT1) directly by binding to their promoter regions contributed to the progression of urothelial bladder carcinoma." (PMID 34776951, 2021).
viral infection (10 papers, 2018 to 2026). "Lysine demethylase 6A (KDM6A) is a critical epigenetic regulator implicated in development, cancer, and viral infection." (PMID 41691482, 2026). "In consistent, immunostaining analysis 2 weeks after viral infection showed significantly reduced level of Kdm6a in RGCs in AAV2‐Cre injected retinas." (PMID 39951327, 2025). "GSK-J4 also has the potential to maintain the dormancy of viral infections by inhibiting the KDM6A/B-mediated reactivation of the latent virus." (PMID 35915507, 2022). "Finally, we used pseudovirus assays to determine whether KDM6A regulates viral infection at the level of entry." (PMID 37410700, 2023). "Targeting the KDM6A/KMT2D/p300 axis offers several potential advantages in the regulation of receptor expression and diverse virus infection." (PMID 37410700, 2023).
bladder tumors (9 papers, 2018 to 2025). "RT-associated bladder tumors were significantly enriched for alterations in KDM6A and ATM, whereas CTRL tumors were enriched for CDKN2A mutation." (PMID 39113632, 2024). "The lower expression of NK cell ligands and receptors suggests that NK cells have reduced activity in bladder tumors with KDM6A and/or SWI/SNF mutations." (PMID 30692641, 2019). "Therefore, EZH2 inhibition, delayed tumor onset in KDM6A-null cells and caused regression of KDM6A-null bladder tumors in multiple mouse models." (PMID 39118085, 2024). "To determine whether the pluripotency markers are altered in bladder tumors and are associated with KDM6A and/or SWI/SNF tumors, we queried our Roswell Park genomics data." (PMID 30692641, 2019). "Therefore, patients who can potentially benefit from EZH2 inhibition would include those whose bladder tumors possess KDM6A and SWI/SNF mutations, Rb1/c-myc alterations and post-translational modifications of EZH2." (PMID 30692641, 2019). "Therefore, we conclude that epigenetic therapy targeting EZH2 alone or in combination with cisplatin can be beneficial in bladder tumors with KDM6A and/or SWI/SNF mutations and/or increased EZH2 activity." (PMID 30692641, 2019). "By promoting KDM6A expression, a significant decrease occurred in metastasis of bladder tumor cells." (PMID 36684065, 2023). "KDM6A is a factor responsible for regulating progression of bladder tumor cells." (PMID 36684065, 2023).